IGLC1 (immunoglobulin lambda constant 1)
Description:
Constant region of immunoglobulin light chains. Immunoglobulins, also known as antibodies, are membrane-bound or secreted glycoproteins produced by B lymphocytes. In the recognition phase of humoral immunity, the membrane-bound immunoglobulins serve as receptors which, upon binding of a specific antigen, trigger the clonal expansion and differentiation of B lymphocytes into immunoglobulins-secreting plasma cells. Secreted immunoglobulins mediate the effector phase of humoral immunity, which results in the elimination of bound antigens. The antigen binding site is formed by the variable domain of one heavy chain, together with that of its associated light chain. Thus, each immunoglobulin has two antigen binding sites with remarkable affinity for a particular antigen. The variable domains are assembled by a process called V-(D)-J rearrangement and can then be subjected to somatic hypermutations which, after exposure to antigen and selection, allow affinity maturation for a particular antigen.
Synonyms: IGLC
Gene: Immunoglobulin constant (C) gene on chromosome 22 (22,895,375 to 22,895,834, forward strand). Ensembl gene ENSG00000211675.
Subcellular location: Secreted; Cell membrane
Genetic constraint (gnomAD): Missense variants: 139 observed, 132.84 expected, observed/expected ratio (o/e) 1.05, 90% interval 0.91 to 1.21. Synonymous variants: 69 observed, 59.17 expected, observed/expected ratio (o/e) 1.17, 90% interval 0.96 to 1.42.
Homologues: Orthologues: mouse Iglc1 (72% identical), rabbit IGLL1 (70% identical), rat Iglc1 (66% identical), mouse Iglc3 (65% identical), mouse Iglc4 (65% identical), mouse Iglc2 (63% identical). Paralogues in human: IGLL5 (99% identical), IGLC2 (96% identical), IGLC3 (95% identical), IGLC7 (93% identical), IGLL1 (83% identical), IGHA2 (36% identical), IGKC (35% identical), IGHM (34% identical), IGHA1 (33% identical), IGHG1 (32% identical), IGHG2 (32% identical), IGHG3 (32% identical), and 65 more.
Diseases named in the same sentence as IGLC1 in open-access papers:
IGLC1 is named in the same sentence as 6 diseases in open-access papers, as found by Europe PMC text mining. Sharing a sentence is not in itself a finding about the gene and the disease. The quoted sentences say what the papers report.
mild cognitive impairment (1 paper, 2020). "At variance, we observed a decrement of CLU, IGHG3, and LMW IGLC1 in A in comparison to Y and C. Among these proteins, CLU is known to enhance amyloid clearance and modulate neuroinflammation in mild cognitive impairment." (PMID 33260845, 2020).
tumor (3 papers, 2023 to 2025). "In contrast, IGLC1+ CAFs, another fibroblast subpopulation, exhibited a decreasing trend with tumor progression and were linked to better prognosis." (PMID 40552583, 2025). "An intriguing finding in our study is the observation that, during tumor progression, the MMP11+ mCAFs subpopulation exhibits an inverse trend compared to the IGLC1+ CAFs subpopulation, which is associated with a better prognosis." (PMID 40552583, 2025). "Tumor stemness was negatively correlated with the expressions of 4 IGLCs (IGLC1, IGLC2, IGLC3, and IGLC7) respectively in CESC tissues." (PMID 37784026, 2023). "In RNAss database, tumor stemness was confirmed to be negatively correlated with the expressions of IGLC1 (r = -0.15, P = 0.01), IGLC2 (r = -0.16, P = 0.01), IGLC3 (r = -0.15, P = 0.01), and IGLC6 (r = -0.13, P = 0.03) respectively." (PMID 37784026, 2023). "In DNAss database, we found that tumor stemness was negatively correlated with the expressions of IGLC1 (r = -0.14, P = 0.02), IGLC2 (r = -0.13, P = 0.02), IGLC3 (r = -0.13, P = 0.02), and IGLC7 (r = -0.14, P = 0.01) respectively in CESC tissues." (PMID 37784026, 2023). "Except for IGLC4, IGLC5, and IGLC7, 4 IGLC (IGLC1, IGLC2, IGLC3, and IGLC6) expressions were positively correlated with infiltration scores of 6 tumor-infiltrating immune cells (B cell, T cell CD4, T cell CD8, neutrophil, macrophage, and DC)." (PMID 37784026, 2023). "Notably, in the later stages of tumor progression, the poor‐prognosis MMP11+ mCAFs predominate, whereas IGLC1+ CAFs are more prevalent in the early stages." (PMID 40552583, 2025). "However, the expressions of IGKC, IGLC1, ITGB2, CTSS, HLA‐DPB1, and RSAD2 were elevated in tumor tissue and they served as protective factors." (PMID 37543714, 2023).
hematologic malignancies (1 paper, 2018). "On the other hand, IGJ, IGLJ3, and IGLC1 were found to be either characteristic or prognostic of a number of solid and hematologic malignancies." (PMID 29483918, 2018).
IGLC1 also shares sentences with these, for which no sentence is quoted: breast carcinoma (1 paper); chronic myeloid leukemia (1); colon cancer (1).